MYC (MYC proto-oncogene, bHLH transcription factor)
Diseases named in the same sentence as MYC in open-access papers (continued):
Sharing a sentence is not in itself a finding about the gene and the disease.
lymphoma (continued). "Combination therapy targeting both MYC and BCL2 may provide a new strategy to improve the clinical outcome of MYC/BCL2 double-hit lymphomas and MYC/BCL2 dual expressers." (PMID 38918775, 2024). "In a mouse B-cell lymphoma model, they showed that combining L-asparaginase with phenformin, an electron transferring chain (ETC) inhibitor that depletes intracellular aspartate, an indispensable precursor for asparagine, significantly reduced c-MYC expression and lymphoma burden." (PMID 38539506, 2024). "High-grade B-cell lymphoma with 11q aberration (HGBCL-11q) is a rare germi-nal centre lymphoma characterised by a typical gain/loss pattern on chromo-some 11q but without MYC translocation." (PMID 39796140, 2024). "Moreover, the increased sensitivity of C23 upon MYC expression was alleviated by the mTOR inhibitor Rapamycin in two independent murine lymphoma cell lines." (PMID 39341827, 2024). "In keeping with this, MYC protein was strongly expressed in most lymphoma cells in this case." (PMID 38184753, 2024). "Importantly, both genetic and pharmacological studies have established that the polyamine–hypusine circuit is essential for development and maintenance of MYC-driven lymphoma." (PMID 39125743, 2024). "Moreover, classifications that used to be under “Burkitt-like” lymphoma are now categorized as either high-grade B-cell lymphoma with MYC and BCL-2 and/or BCL-6 rearrangement, Burkitt-like lymphoma with 11q aberration, or simply high-grade B-cell lymphoma." (PMID 38535155, 2024). "Interestingly, in this category, there is a subset of cases, approximately 30%, in which the BCL6 gene is the MYC partner gene, and this group is termed pseudo-hit lymphoma." (PMID 39684922, 2024). "The 250 nmol/L in vitro enitociclib concentration used in these experiments is based on the clinical exposure of enitociclib in 15 patients with MYC+ lymphoma; however, this is an estimate and may be superphysiologic." (PMID 37882668, 2023). "Given the essential role of BCL-W in spermatogenesis, and the lack of other defects in Bcl-w−/− mice, it may be tempting to speculate on a link between the production of male sex hormones and the minor delay in MYC-driven lymphoma development." (PMID 37567974, 2023). "NOTCH1, which directly targets MYC, is considered a common noncanonical Notch signal mediator and is closely associated with lymphoma tumorigenesis and SACC progression." (PMID 36879115, 2023). "Interestingly, we found that sgTfap4/Eμ-MYC/Cas9 lymphoma cell lines all represented neoplastic counterparts of surface Ig negative pre-B cells." (PMID 36894688, 2023). "Dual translocation of MYC and BCL2 in patients with DLBCL is termed “double-hit lymphoma” (DHL), and dual protein overexpression of MYC and BCL2 without underlying translocations is termed “double-expressor lymphoma” (DEL)." (PMID 36315313, 2023). "Two hundred and forty-three (25.6%) were BCL2/MYC double-expressor lymphoma." (PMID 37032379, 2023). "However, in many cancers like lymphomas or carcinomas, MYC gene is aberrantly activated by transcriptional deregulation, gene amplification, chromosomal translocation, or post-translational modification." (PMID 36969025, 2023). "The study illustrated the value of FNA in diagnosis of BL as well as the importance of integrating results of ancillary studies noting that MYC may be rearranged in other aggressive lymphomas." (PMID 37113725, 2023). "Although this needs to be experimentally demonstrated in the context of a B cell lymphoma, it suggests that targeting the intact paralog in those lymphoma cases that harbor a c-MYC activation would eliminate cancer cells and represent a rather specific therapeutic strategy." (PMID 37035206, 2023). "Equally rare bona fide B-cell lymphoblastic leukemias/lymphomas with TdT expression and MYC translocations or, even rarer, MYC/BCL2 double hit have been mainly reported in the pediatric or adolescent setting and are molecularly different from DLBCL/HGBL-MYC/BCL2." (PMID 37190213, 2023).
lymphoma (continued). "Importantly, upregulation of St6galnac4 is a core component of this glycogene signature and was preserved in both types of MYC-driven leukemia and lymphoma." (PMID 36897988, 2023). "Among these, activated B-cell-like (ABC) subtype, double expressor lymphoma (DEL, double expression of the MYC and BCL2 oncogenes), and double- or triple-hit lymphomas (DH/THLs, genetic rearrangements of MYC and BCL2 and/or BCL6) have been proven to obtain adverse clinical outcomes." (PMID 37361573, 2023). "Over-expression of BCL-2 greatly accelerates c-MYC driven lymphoma development in mice." (PMID 36342579, 2023). "The fact that HLH* EIF3A is sufficient to lower MYC levels in these lymphoma cells and increase their sensitivity to chemotherapeutic compounds suggests that eIF3 could serve as a potential target for cancer therapeutic strategies." (PMID 37768948, 2023). "Whereas our results suggest that combining NK cell-based immunotherapeutic approaches with strategies aimed at targeting MYC might be inappropriate, data by others suggest that targeting MYC in lymphoma cells exerts beneficial effects on NK cell responses." (PMID 37105715, 2023). "We therefore expected that CJL could influence MYC-driven lymphoma by disrupting CRY2-mediated turnover of c-MYC." (PMID 37811199, 2023). "As a transcription factor, MYC regulates the expression of a variety of genes involved in cell metabolism, proliferation, apoptosis and differentiation, and plays important carcinogenic roles in lymphoma." (PMID 36352191, 2023). "Such an assumption is supported by data confirming that MYC suppression could reverse tumorigenesis, which was detected in a variety of tumors such as lymphoma, leukemia, epithelial tumors, and mesenchymal tumors." (PMID 37111592, 2023). "Curiously, the T lymphomas were also Mac-1-positive, which may be due to high MYC expression, because activated CD8+ T cells express Mac1." (PMID 36755068, 2023). "If MYC is positive on immunohistochemistry, it is a triple-hit lymphoma with a very poor prognosis." (PMID 36701728, 2023). "Moreover, using T lymphoma-prone VavP-MYC transgenic mice, we show that Mnt deletion reduces the pool of pre-malignant MYC-driven T lymphoid cells and abrogates thymic T lymphomagenesis." (PMID 36755068, 2023). "Since fully transformed Eμ-MYC lymphomas are monoclonal they express only one Ig species." (PMID 36894688, 2023). "Furthermore, CCDC86 was identified to be an autonomous tumour growth driver that cooperates with MYC to drive aggressive lymphoma growth in vivo." (PMID 36695333, 2023). "We investigate mosaic chromosomal alterations in sub-Saharan Africa among 931 children with Burkitt lymphoma, an aggressive lymphoma commonly characterized by immunoglobulin-MYC chromosomal rearrangements, 3822 Burkitt lymphoma-free children, and 674 cancer-free men from Ghana." (PMID 38057307, 2023). "Furthermore, when modified with a chimeric antigen receptor (CAR), selective tropism is given leading to specific particle accumulation in tumor cells, followed by CRISPR/Cas9 system release and subsequent targeting of the MYC oncogene in lymphoma." (PMID 36969025, 2023). "This indicates that increased cell proliferation is not the mechanism by which loss of TFAP4 accelerates c-MYC-driven lymphoma development." (PMID 36894688, 2023). "Interestingly, the anti-BCL2 family inhibitor ABT263, was similarly potent in preventing tumor progression in TH-MYCN+/+ mice, a finding that is reminiscent of MYC-driven lymphoma models." (PMID 37958555, 2023). "In the context of c-MYC-driven lymphoma development, loss of TFAP4 does not alter apoptosis or cell proliferation, as the genes regulating these processes were not differentially expressed in pre-leukaemic pre-B cells lacking TFAP4." (PMID 36894688, 2023). "Indeed, suppressing glutathione synthesis with BSO increased IACS‐010759 activity on MYC‐overexpressing B‐cells and lymphoma cell lines." (PMID 37158102, 2023).
lymphoma (continued). "In our study, we have focused on transformation-associated DNA alterations observed in an important subset of B-NHL—‘double-hit’ lymphomas that harbor MYC rearrangements in addition to the BCL2 rearrangement characteristically observed in FL and which are highly aggressive and difficult to treat." (PMID 38049665, 2023). "To this end, we sought to identify factors that could confer resistance to MCL-1 inhibitors using murine and human models of highly aggressive, MYC-driven lymphoma." (PMID 36755070, 2023). "However, when looking into the downstream effects of decitabine, we did observe downregulation of the oncogenic MYC pathway, contributing to the overall anti-lymphoma effect in T-LBL." (PMID 36765607, 2023). "Finally, either DHEA or 6AN potentiated killing by IACS‐010759 also in human MYC‐rearranged lymphoma cell lines." (PMID 37158102, 2023). "Furthermore, inhibition of PLK1 with BI6727 (volasertib) synergized with the BCL2 inhibitor ABT199 (venetoclax) to kill MYC/BCL2 double‐hit lymphoma cell lines." (PMID 36214609, 2022). "LncRNAs such as MINCR may essentially contribute to both MYC-positive lymphomas and numerous types of MYC-dependent cancers." (PMID 34923811, 2022). "Review of the literature data regarding MYC insertion in lymphomas." (PMID 35167621, 2022). "Selective suppression of MYC expression could be a potential component of lymphoma therapy, including the treatment of drug-resistant tumors." (PMID 35563017, 2022). "We hypothesised that altered activation of CHK1 by ATR in response to MYC-induced DNA replication stress in Eμ-Myc/cRel−/− lymphoma cells could affect CHK1 inhibitor sensitivity." (PMID 36240066, 2022). "Moreover, combining PRMT5 inhibition with MSI2 or BCL-2 inhibitors blocks the translation of key drivers of lymphoma, c-MYC and BCL-2, inhibiting cell growth." (PMID 36167829, 2022). "Considering the significance of chromosome analysis in the detection of insertion, it is possible that the presence of the MYC insertions in lymphomas is undervalued because routine genetic diagnosis of suspBL in most laboratories is based on FISH only; karyotyping is rarely performed." (PMID 35167621, 2022). "Omomyc inhibits c-MYC in part by promoting its proteasomal degradation in lymphoma cell lines." (PMID 35267559, 2022). "Additionally, HIV-1 Tat enhances c-MYC transcription by binding to the c-MYC promoter, which can contribute to a more aggressive lymphoma phenotype." (PMID 36275462, 2022). "CBX2-depleted samples revealed the downregulation of gene sets mainly related to proliferation, such as E2F and MYC targets, inflammation, and oxidative phosphorylation, which is upregulated in several cancers including leukemia and lymphoma." (PMID 35681235, 2022). "Our findings identified the HDAC6 inhibitor M-100 as a new tool to target MYC-dependent lymphomas." (PMID 36068335, 2022). "Umbralisib gave promising results in reducing viability of multiple MYC-driven lymphomas." (PMID 35720131, 2022). "Uncontrolled MYC elevated expression is often observed in leukemia and lymphoma." (PMID 36452487, 2022). "Additionally, three patients were diagnosed with double-hit lymphoma in the murinized group, carrying MYC and BCL2 or BCL6 translocations simultaneously, compared to four patients in the humanized group." (PMID 36552849, 2022). "However, there are few data in the literature describing the MYC fusions arising from cryptic MYC insertion in different types of lymphomas." (PMID 35167621, 2022). "The potential relevance of mitochondrial activities as therapeutic targets in MYC‐driven lymphoma was delineated further by transcriptome analysis across six patient‐derived DLBCL datasets, which revealed a close correlation between MYC‐ and OxPhos‐associated gene expression signatures." (PMID 36214609, 2022). "Furthermore, in BCL2‐negative, MYC‐translocated lymphoma cell lines, the cytotoxic activity of IACS was potentiated by the Mcl‐1 inhibitor S63845." (PMID 34632715, 2022).
lymphoma (continued). "Since MYC-driven tumours become addicted to CHK1 signalling, an important question arising from our studies was how the mutant NF-κB subunit Eμ-Myc lymphomas that are deficient in this signalling pathway are still able to survive, especially as both models display earlier onset of disease." (PMID 36240067, 2022). "Furthermore, PRMT5 increases de novo syntheses of key lymphoma-drivers, MYC and CYCLIN D1 by repressing miR-33b, miR-96, and miR-5038,10." (PMID 36167829, 2022). "Indeed, CPI-613 recapitulated the rapid apoptosis elicited by glutamine withdrawal in MYC-overexpressing cells in vitro and achieved tumour suppression in MYC-driven lymphoma in vivo." (PMID 35945217, 2022). "Indeed, in a murine model, pharmacological inhibition of Aurora kinases proved highly effective against MYC‐driven lymphoma." (PMID 36214609, 2022). "Here, we report for the first time that tumors from lymph nodes of λc-MYC (Avy/a) mice exhibit five transcripts as new tools to exacerbate the imbalanced expression of c-Myc proteins that may explain the aggressive lymphomas in the λc-MYC (Avy/a) mouse model." (PMID 35740961, 2022). "Many “epi-drugs” exist that target epigenetic regulators in B-NHL, which could be further utilized in therapy for MYC-dependent lymphoma or lymphomas with MYC as the secondary driver." (PMID 36611833, 2022). "Similarly, direct inhibition of protein translation by knockdown or pharmacological inhibition of the eIF4F complex was synthetic‐lethal with oncogenic MYC in murine models of lymphoma and myeloma." (PMID 36214609, 2022). "A pre-clinical model of c-MYC-driven lymphoma xenograft demonstrated that combining CX-5461 with an mTOR inhibitor could effectively suppress tumour growth." (PMID 35267559, 2022). "Additionally, the MYC FISH study provided crucial information for differentiating PCNS-DLBCL from other lymphoma subtypes." (PMID 35875161, 2022). "It was reported that DNA damage increases upon combining ATR suppression with MYC overexpression 23 and Chk1 inhibitors were highly effective in killing MYC-driven lymphomas 24, suggesting synthetic lethality as a treatment strategy for MYC-overexpressing tumors." (PMID 35844787, 2022). "We expect that the appearance of the MYC insertions in lymphoma might be underestimated and that more studies on the frequency of this alteration in BL and BLL,11q are needed." (PMID 35167621, 2022). "Still, the impact of epigenetic reprogramming in MYC-induced lymphoma is unknown regarding persistent changes in gene expression, even after uncoupling from the oncogene MYC." (PMID 36611833, 2022). "Here we show that MYC expression is also associated with PDCD4 down-regulation in CLL cells in vivo and characterize the signaling pathways that mediate BCR-induced PDCD4 down-regulation in CLL and lymphoma cells." (PMID 35306137, 2022). "Finally, IACS‐010759 and the BCL2 inhibitor venetoclax effectively cooperated against MYC/BCL2 double‐hit lymphoma in xenograft‐based preclinical models." (PMID 34632715, 2022). "Interestingly, the combination of constitutive MYC expression with PI3K activity in GC B-cells results in development of lymphoma in transgenic murine models, which is highly reminiscent of human BL." (PMID 36428647, 2022). "For example, the human BCL-2 and c-MYC genes contain DNA sequences with the capacity to adopt non-B DNA structures that overlap with areas prone to breakage and chromosomal translocations found in lymphomas and leukemias." (PMID 40766048, 2022). "Activation of the SSP pathway in human MYC-driven GC lymphomas." (PMID 35316216, 2022). "MINCR, known as an lncRNA, has been related to the MYC expression in MYC-positive lymphomas." (PMID 34923811, 2022).
lymphoma (continued). "Pharmacological inhibition of the BET family proteins BRD2, BRD3, BRD4, and BRDt has emerged as a therapeutic approach to target MYC-dependent transcription because BRD4 regulates MYC and a number of other lymphoma-relevant oncogenes (BCL2, CDK4/6, and cyclin D1)." (PMID 35031886, 2022). "MYC also has been shown to cross-talk with HIF1α in this lymphoma." (PMID 36428647, 2022). "Overexpression of MYC is a genuine cancer driver in lymphomas and related to poor prognosis." (PMID 36068335, 2022). "Indeed, RPs alterations are common in leukemic patients and have been reported in several models of MYC-induced lymphoma." (PMID 36226068, 2022). "The serine–glycine-free diet is of particular interest in light of observations showing that it could significantly prolong the survival of mice with MYC-driven lymphoma, and that these mice also respond to inhibition of the serine synthesis pathway." (PMID 36428647, 2022). "Using FISH, 4 separate assays (BCL2,-BA (break-apart), BCL6-BA, MYC-BA, MYC-IGH-F(fusion)) are needed to diagnose DH/TH lymphomas, while still missing those cases that carry a MYC-IGL translocation since no commercial probes are available for MYC-IGL fusion FISH." (PMID 34099699, 2021). "In lymphoid cancers, these same cell growth and survival pathways are disrupted and have uncontrolled activity; for example: in several human lymphomas, chromosomal translocations that activate MYC and BCL-2 are observed." (PMID 34440825, 2021). "Thus, in some endogenous mouse tumor models, DCs displayed a downregulation of costimulatory molecules, whereas a mature phenotype was observed in other neoplasias including the λ-MYC lymphoma." (PMID 33141285, 2021). "The authors of the study showed that PCYT1A was overexpressed in 44% of the analyzed DLBCL patients and that PCYT1A overexpression occurred in parallel with the enhanced gene and protein expression of MYC, an oncogene mostly involved in lymphoma cell chemoresistance." (PMID 33467668, 2021). "Interestingly, CR-1-31 B also shows strong activity against lymphoma cells with known MYC and/or BCL2 alterations that continue to represent a therapeutic challenge." (PMID 33562682, 2021). "Additionally, DNAi 5T was further shown to accumulate in the nuclei of lymphoma cells, additively with the MYC G4 stabilizing compound NSC 338258, and it remains the most effective DNAi to target the MYC G4-forming promoter region." (PMID 34577013, 2021). "Previous studies have reported that DLX5 is upregulated in human lymphomas and non-small cell lung cancer, where it could bind to the MYC promoter to activate its transcription." (PMID 34336814, 2021). "Similarly, expression of NRF2E79V in the MYC+/BCL2+ SuDHL-6 lymphoma cells protects them against silvestrol treatment." (PMID 33562682, 2021). "Besides, only the combinatorial knock-down of HDAC1 and HDAC2 led to a huge increase in apoptosis of MYC-driven lymphoma cells." (PMID 35008680, 2021). "U2904 and Ri-1 are quickly proliferating lymphomas with MYC gene rearrangement." (PMID 34440794, 2021). "Another key feature of double expressor status is that the laboratory infrastructure and immunohistochemical reagents required to perform this testing are widely available due to the important diagnostic roles of both MYC and BCL2 in lymphoma pathology workups." (PMID 34282799, 2021). "Having previously shown that multiple mechanisms, which also involve NK cells, are elicited by ICB therapy, we now asked the question whether DCs contribute to the therapeutic potential of anti-CTLA-4 and anti-PD-1 mAbs in the λ-MYC lymphoma model." (PMID 33141285, 2021). "Notably, a new translocation of the MYC gene into the immunoglobulin locus is observed in ~10% of such transformed lymphomas (so-called “double-hit” lymphomas)." (PMID 33799592, 2021).